ITGB2 (integrin subunit beta 2)
Diseases named in the same sentence as ITGB2 in open-access papers (continued):
Sharing a sentence is not in itself a finding about the gene and the disease.
COVID-19 (15 papers, 2021 to 2025). A disease caused by infection with severe acute respiratory syndrome coronavirus 2. "It has been shown that elevated concentrations of ITGB2 were associated with long-term pulmonary complications in post-COVID-19 patients." (PMID 41012626, 2025). "Expression of ITGB2, another integrin subunit encoding gene, was also downregulated in ILC1s and ILC2s (adj.p = 2.6e-10 and 1.2e-21, respectively) in COVID-19 patients compared with controls." (PMID 39026668, 2024). "The purpose of this study was to investigate the association between soluble ITGa2, ITGaM and ITGb2 integrin subunits and long COVID-19 pulmonary complications." (PMID 36615143, 2023). "The respective APNet bipartite graph contained a large cluster (IL10RA, ACTN4, ITGB2, IL2RB, BIRC2, ITGAM, HMOX1, TIMP1) linked with established COVID-19 inflammatory and immune signalling cascades." (PMID 39921901, 2025). "Soluble ITGAM and ITGB2 elevation have also been shown to correlate significantly with long-term pulmonary COVID-19 complications and may represent promising biomarkers for predicting such complications." (PMID 38882332, 2024). "It is also notable that many of the transcriptional signatures, including RHOB, MPP6, TNFRSF1B, ITGB2, and ZEB2 elevated in AM2 from COVID-19 patients have also been detected as transcriptional markers of AM B cells." (PMID 35899045, 2022). "We also found an increased expression of CD63, ITGB2, CD37, CD2 and IL23R markers and the reduction in CXCR4, CD69, CD48, ICAM1 and S100A10 markers in COVID-19-derived NK-T cells compared to controls." (PMID 34944610, 2021). "There were no signal inflows unique to either moderate or severe COVID-19 alone, whereas inflow through TNFRSF12A (due to TNFSF12) and ITGAX and ITGB2 (due to C3) drive outflows in only healthy controls." (PMID 39187683, 2024).
Stroke (14 papers, 2013 to 2025). Sudden impairment of blood flow to a part of the brain due to occlusion or rupture of an artery to the brain. "At 1 day after tMCAO, our enrichment analysis and MCODE analysis of sc_S4 and sc_S5 cells representing Itgb2+ on day 1 after tMCAO showed that Itgb2+ microglia clusters representing the early stroke phase were undergoing rapid proliferation and differentiation, and intense energy metabolism." (PMID 37063847, 2023). "Similarly, genes involved in integrin cell surface interactions including Itga10, Itgb3, Vcam1, Itgb1, Itgae, Itgb7, Itga1, Itga5, Icam1, Itgb2, Pecam1, and Icam2 were depleted in male MMP-3 KO stroke brains." (PMID 39000490, 2024). "At 8 weeks post-stroke, the top 10 genes were Cd44 (degree = 14), Fcgr2b (degree = 13), C1qb (degree = 13), Cd74 (degree = 12), C1qc (degree = 11), Cd14 (degree = 10), C4a (degree = 10), Spp1 (degree = 10), RT1-A2 (degree = 9), and Itgb2 (degree = 9)." (PMID 31888302, 2019). "However, some genes are unresolved by 7 days post-stroke comprising primarily cell adhesion and ECM-endothelial interaction molecules such as ITGB2, ITGA5 indicating persistent disruption of the BBB but also glutamatergic pathways as a hint for ongoing cytotoxicity." (PMID 32300291, 2020). "At 4 weeks post-stroke, the top 10 gene products in the PPI network were Cd44 (degree = 17), C1qb (degree = 15), Fcgr2b (degree = 14), Spp1 (degree = 12), Cd74 (degree = 12), C4a (degree = 12), C1qa (degree = 12), C3 (degree = 10), Cd14 (degree = 10), and Itgb2 (degree = 10)." (PMID 31888302, 2019).
asthma (13 papers, 2006 to 2025). "Our results highlight RELA, ETS1, NFATC1, and ITGB2 as central players in the pathogenesis of various diseases, including RA, lymphoma, asthma, acute myelocytic leukemia, and leukemogenesis." (PMID 40839671, 2025). "A “proof-of-concept” assay was also performed, with TH2 biomarkers ITGA4 and ITGB2 displaying a differential abundance in sEVs from T2high and T2low asthma patients." (PMID 39409176, 2024). "As a proof-of-concept, sEVs from serum samples of T2high asthma patients tend to present higher levels of TH2-related proteins (ITGA4 and ITGB2) than the T2low counterparts, as expected." (PMID 39409176, 2024). "The levels of most proteins (ITGAM, ITGB2, MMP12, NCF1, NCF2, NCF4, RAC2 and Vav1) were higher in the asthma condition (shown in red) than those in the control condition or after SCIT condition." (PMID 34618857, 2021). "The expression levels (the staining intensity) of ITGB2, RAC2 and Vav1 were higher in the asthma group than other groups." (PMID 34618857, 2021). "The expression levels of ITGA4 and ITGB2 in IL‐5‐activated eosinophils and that of CCR3 in IL‐5‐ or IL‐17‐activated eosinophils were significantly higher for patients with asthma than for normal individuals." (PMID 39575691, 2024). "Additionally, the genes involved in proinflammatory function (ITGB2 and FABP4) and apoptosis process (IFI27) were elevated in asthma." (PMID 36439114, 2022).
glioma (13 papers, 2018 to 2026). A benign or malignant brain and spinal cord tumor that arises from glial cells (astrocytes, oligodendrocytes, ependymal cells). "Furthermore, higher expression of ITGB2 was associated with shorter overall survival of glioma patients." (PMID 33801334, 2021). "Interestingly, single nucleotide polymorphisms of ITGB2 have been shown to be associated with risk of glioma." (PMID 29676997, 2018). "Meanwhile, ligand-receptor interactions between THY1 (CD90) and ITGAX/ITGB2 (CD11C/CD18) were observed from glioma cells (Clusters C1, C2, and C4) to TAMs (Cluster C0)." (PMID 38515213, 2024). "These adhesion molecules are known to potentiate cancer stem cell function, supporting the role of the THY1-ITGAX/ITGB2 axis in glioma cell adhesion, survival, and differentiation." (PMID 38515213, 2024). "Glioma is the most common primary tumor in the brain.Integrin beta 2(ITGB2) is a member of the leukocyte integrin family (leukocyte integrin), participating in lymphocyte recycling and homing, cell adhesion, and cell surface-mediated signal transduction." (PMID 36714574, 2022). "This study first discussed the relationship between ITGB2 expression and different grades and types of gliomas." (PMID 36714574, 2022). "We verified the predictive function of ITGB2 to mesenchymal subtypes and the prognostic role of ITGB2 by using the Chinese Glioma Genome Atlas (CGGA), Rembrandt, and The Cancer Genome Atlas (TCGA) database analysis." (PMID 36714574, 2022). "ITGB2 can be used as a potential marker of mesenchymal molecular subtypes of gliomas and as an independent predictive marker of OS in patients with malignant gliomas and provides new insights into the immunotherapy of LGG." (PMID 36714574, 2022). "To explore the biological process related to the expression of ITGB2 in gliomas, we conducted Pearson related analysis between ITGB2 expression and other genes in whole-genome gene profiling of 325 patients in the CGGA RNA-seq set." (PMID 36714574, 2022). "Using cox regression analysis to verify the ability of ITGB2 as an independent predictor of OS in glioma patients." (PMID 36714574, 2022). "Biological processes show that ITGB2 has involved glioma immune-related activities, especially closely related to B cells, CD4+Tcells, macrophages, neutrophils, and dendritic cells." (PMID 36714574, 2022). "We performed ITGB2 expression and receiver operating characteristic curve (ROC) analysis of mesenchymal subtypes in all grades of gliomas to verify this finding further." (PMID 36714574, 2022). "ITGB2 can be used as a potential marker of mesenchymal molecular subtypes of gliomas and as an independent predictive marker of OS in patients with malignant gliomas." (PMID 36714574, 2022). "ITGB2 is a common and important gene in glioma immunity and stromal infiltration." (PMID 39458936, 2024). "They found that the glioma grade increases relatively to the expression level of ITGB2, and suggested that ITGB2 could represent a novel predictor for glioma." (PMID 36945359, 2023). "In summary, all above results suggest that ITGB2 can affect glioma-related immune activity." (PMID 36714574, 2022). "ITGB2 can be a potential marker for mesenchymal molecular subtype gliomas." (PMID 36714574, 2022). "However, few studies on ITGB2 in gliomas have been reported yet, remaining clinical and prognostic significance unclear, especially in LGG." (PMID 36714574, 2022). "However, few studies on ITGB2 in gliomas have been reported yet.This study first discussed the relationship between ITGB2 expression and clinical characterization of glioma and the prognostic significance of its methylation in low-grade glioma." (PMID 36714574, 2022). "Interestingly, recent data indicated ITGB2 as being highly positively correlated with the tumor-associated macrophage (TAM) marker CD68, suggesting an increased infiltration of TAMs in ITGB2-positive gliomas." (PMID 33801334, 2021).
glioma (continued). "Our analysis identifies critical ligand-receptor pairs between TAMs and glioma cells that promote tumor progression, such as MIF-CD74/CXCR4, THY1-ITGAX/ITGB2, and ANGPTL2-TLR4." (PMID 38515213, 2024). "We collected Clinical data and transcription of glioma patients from TCGA, CGGA, and Rembrant datasets to analyze the differential expression of ITGB2 mRNA in glioma tissues and normal tissues." (PMID 36714574, 2022). "Interestingly, we also observed an increased abundance of TAM-SPP1 in recurrent glioma patients and their interaction with tumor cells via THY1-ITGAX/ITGB2 signaling." (PMID 38515213, 2024). "ITGB2 can significantly predict OS in all grades of gliomas(Since Rembrant’s Microarray dataset does not have IDH mutation status information, we cannot verify it in Rembrant’s Microarray dataset)." (PMID 36714574, 2022). "The identification of the downstream signals of HK2 demonstrated that the high expression of hub genes, including ITGB2, CD53, C3AR1, CYBB and ITGAM, maybe a potential target for the treatment of glioma." (PMID 35982398, 2022).
lung carcinoma (13 papers, 2015 to 2025). "Macrophage-lung cancer hybrids also expressed the β2 integrin subunit (Itgb2), and at levels similar to that of unfused monocytes." (PMID 37427108, 2023). "To further explore the potential mechanisms and possible molecular function of ITGB2 in lung cancer tumorigenesis, we performed GO and KEGG analyses to explore the pathways enriched in the differentially expressed genes of ITGB2-DEGs." (PMID 36362654, 2022). "Next, we examined the effect of ITGB2 on lung cancer cell migration and invasion using Transwell assays." (PMID 36362654, 2022). "To facilitate clinical application, in the lung cancer transcriptome, including 19,464 protein-coding genes, we extracted the three most relevant genes of B cell (CD19, TLR10, and FCRLA) and DC1 (ITGB2, LAPTM5, and SLC7A7), respectively." (PMID 34422829, 2021). "Druggability evaluation suggests that existing drugs targeting ITGB2, GP1BA, ACADSB and COX6B1 could potentially be repurposed for the treatment of specific lung cancer subtypes." (PMID 41340014, 2025). "Additionally, the repurposing of approved drugs targeting ITGB2, GP1BA, ACADSB and COX6B1 for the treatment of different lung cancer subtypes provides new therapeutic options, potentially leading to more effective treatments for patients with advanced lung cancer." (PMID 41340014, 2025).
melanoma (13 papers, 2005 to 2025). A malignant, usually aggressive tumor composed of atypical, neoplastic melanocytes. "Melanoma patients with high expressions of Wdfy4, Parp14, Cybb, Itgb2, and Itgam were found to be associated with the longer OS time in melanoma." (PMID 33679872, 2020). "Our analysis revealed that a higher expression of ICAM, ITGAL (LFA-1α), and ITGB2 (LFA-1β) was significantly correlated with a low risk for most cancer types, particularly melanoma." (PMID 40277945, 2025). "Patients exhibiting concurrent high infiltration of CD4+ Th1 and CD8+ T cells and elevated ICAM, ITGAL, and ITGB2 expression had the best clinical outcomes out of the patients with melanoma." (PMID 40277945, 2025). "Higher levels of RFTN2 and ITGB2 transcripts are also found in metastatic human melanomas compared with primary skin tumors." (PMID 39819494, 2025). "The PPI network analysis revealed that 6 hub genes, comprising Itgb2, Wdfy4, Itgam, Cybb, Mmp2, and Parp14, might be key candidate genes related to the pathogenesis of melanoma." (PMID 33679872, 2020). "The DFS time analysis revealed that there was a similar trend that high expressions of Wdfy4, Parp14, Cybb, Itgb2, and Itgam were correlated to longer DFS time in melanoma." (PMID 33679872, 2020). "Based on the TCGA database, we found that Wdfy4, CYBB, Itgb2, and Itgam were down-regulated and MMP2 was up-regulated in melanoma samples compared with normal samples." (PMID 33679872, 2020).
psoriasis (13 papers, 2013 to 2025). An autoimmune condition characterized by red, well-delineated plaques with silvery scales that are usually on the extensor surfaces and scalp. "To further assess the role of Ca2+ influx-induced [Ca2+]ex drop in psoriasis pathology, we established psoriasis model by applying IMQ cream to the ear using R26-LSL-CEPIAexternal;Itgal-LSL-Clover;Itgb2-LSL-mRuby2;CD4-Cre mice and injected with SKF96365 or DMSO daily for 7 days." (PMID 39033133, 2024).
leukemia (12 papers, 2012 to 2026). A malignant (clonal) hematologic disorder, involving hematopoietic stem cells and characterized by the presence of primitive or atypical myeloid or lymphoid cells in the bone marrow and the blood. "ITGB2 (integrin beta chain 2) regulates cell adhesion and signaling in combination with different alpha chains, and has been associated with the formation of invadosomes that facilitate leukemia cell invasion through transendothelial migration." (PMID 27447550, 2016). "HSPC-Lipo increased affinity of liposomes for leukemia (Ka539) cell line ~2.7-fold in vitro (from a baseline of ~13% when ITGB2 knocked down, up to ~35%)." (PMID 38971796, 2024). "Differential gene expression analysis found that many upregulated genes in the C2 subtype were associated with increased leukemia cell survival, proliferation, and drug resistance, such as S100A8, S100A9, LILRB3, KLF4, LST1, and ITGB2." (PMID 37691822, 2023). "Moreover, the biomimetic vesicles exhibit superior binding affinity to leukemia cells through intercellular cell adhesion molecule-1 (ICAM-1)/integrin β2 (ITGB2) interaction." (PMID 38971796, 2024). "Additionally, it has been reported that high levels of integrin beta 2 (ITGB2) are related to poor outcome in leukemia." (PMID 25076125, 2014). "ICAM-1 and ITGB2 are documented as ligand-receptor, and previous studies have shown that ICAM-1 is highly expressed on the surface of leukemia cells." (PMID 38971796, 2024). "Mechanistically, through analysis of surface proteins by mass spectrometry, the interactions between CD44-hyaluronic acid and ITGB2-ICAM-1 mediate the targeting of biomimetic vesicles to the bone marrow and leukemia cells, respectively." (PMID 38971796, 2024). "ITGB2 is a classical adhesion ligand, and its receptor is ICAM-1 (CD54), which is highly expressed in leukemia cells." (PMID 38971796, 2024). "Fibrinogen and collagen in plasma will bind to the surface of GDYO nanosheets, increasing the interaction of GDYO on ITGB2 and MRC2, respectively, and thereby enhancing the anti-leukemia effect of GDYO against DNMT3A-mutant AML cells." (PMID 36163326, 2022). "In summary, the binding of GDYO to both ITGB2 and MRC2 is indispensable for its anti-leukemia effect." (PMID 36163326, 2022). "GDYO enhanced interaction on ITGB2 and MRC2 with mouse plasma protein absorption, and improved the anti-leukemia effect in vitro, which partially revealed the mechanism of effective therapeutic effect in mice AML model." (PMID 36163326, 2022). "Two days after treatment, the binding activity of all four cell lines was significantly reduced by the treatment with anti-ITGA6 or anti-ITGB4 antibodies; however, isotype IgG, anti-ITGB2 or anti-ITGB3 antibodies did not inhibit the binding of EVI1high leukemia cells to matrigel." (PMID 22295105, 2012). "Two leukemia (UCSD/AML1 and MOLM1) and two primary human AML (PT9 and PT11) cells lines were cultured on matrigel and treated with or without anti-ITGA6, ITGB2, ITGB3, or ITGB4 antibodies." (PMID 22295105, 2012).
Leukocyte adhesion deficiency type I (12 papers, 2006 to 2025). Leukocyte adhesion deficiency type I (LAD-I) is a form of LAD (see this term) characterized by life-threatening, recurrent bacterial infections. "Absent or dysfunctional expression of LFA-1, caused by mutations in the ITGB2 (integrin subunit beta 2) gene, results in a rare immunodeficiency syndrome known as Leukocyte adhesion deficiency type I (LAD I)." (PMID 35408940, 2022). "Moreover, we believe our findings to be highly relevant to individuals with leukocyte adhesion deficiency type-I, a primary immunodeficiency caused by mutations on the ITGB2 gene which encodes the common β2 integrin subunit in humans." (PMID 30233576, 2018). "Leukocyte adhesion deficiency type I (LAD-I) is a primary immunodeficiency caused by mutations in the ITGB2 gene and is characterized by recurrent and life-threatening bacterial infections." (PMID 27056660, 2016). "Mutations within the ITGB2 gene, which encodes for the β2 integrin subunit CD18, produce leukocyte adhesion deficiency type 1 (LAD-1), an inherited immunodeficiency." (PMID 40801580, 2025). "The WES result demonstrated a compound heterozygosity for two variants in the ITGB2 gene (c.817G>A; p.Gly273Arg and c.314T>C; p.Leu105Pro) consistent with the molecular diagnosis of autosomal recessive leukocyte adhesion deficiency type I (LAD-I)." (PMID 39081307, 2024). "Leukocyte adhesion deficiency type I (LAD-I) is a rare autosomal recessive inborn error of immunity (IEI) caused by the defects in CD18, encoded by the ITGB2 gene." (PMID 36353617, 2022). "Leukocyte adhesion deficiency type I (LAD-I) is the most common type of LAD, and is caused by mutation in the gene encoding the β2-subunit of the integrin (CD18), ITGB2." (PMID 24478771, 2014).
Obesity (12 papers, 2013 to 2025). Accumulation of substantial excess body fat. "Even humans with a polymorphism in ITGB2 that results in reduced CD18 expression are at increased risk of obesity." (PMID 28873429, 2017). "Methotrexate and aspirin demonstrated multi-target activity against myeloid activation (FCGR2A, ITGB2), aligning with recent obesity-cancer immunomodulation studies." (PMID 41199823, 2025). "Some of the hub genes identified were AURKA, MELK, and TKT for prenatal LOW vs HIGH nutrition, and CTSS and ITGB2 for late gestation malnutrition followed by early obesity development (LOW-HCHF and HIGH-HCHF vs NORM-CONV)." (PMID 33975549, 2021). "Using WGCNA, we confirmed AURKA, ITGB2, CTSS, and TYROBP as hub genes, which were identified in the coexpressed modules in PER♂, whereas AURKA was identified as a hub gene in PER♀, and these hub genes have been associated with obesity comorbidities." (PMID 37458462, 2023). "In summary, in this study, six hub genes, including Mki67, Rac2, Itgb2, Emr1, Tyrobp and Csf1r were identified which could be used as therapeutic biomarkers for obesity." (PMID 36654490, 2023). "In particular, an SFA diet led to an upregulation of genes such as integrin beta 2 (ITGB2), cathepsin S (CTSS), and interleukin-8 (IL-8) in moderately overweight individuals, suggesting that these changes were linked to diet-induced changes rather than obesity." (PMID 29643982, 2018).
diabetes (11 papers, 2012 to 2025). "Based on the most recent experimental research, ITGB2 is essential for the progression of diabetes, and the ITGB2 gene deficiency may hopefully prevent the disease." (PMID 36911691, 2023).